HMGCL (3-hydroxy-3-methylglutaryl-CoA lyase)
Description:
Mitochondrial 3-hydroxy-3-methylglutaryl-CoA lyase that catalyzes a cation-dependent cleavage of (S)-3-hydroxy-3-methylglutaryl-CoA into acetyl-CoA and acetoacetate, a key step in ketogenesis. Terminal step in leucine catabolism. Ketone bodies (beta-hydroxybutyrate, acetoacetate and acetone) are essential as an alternative source of energy to glucose, as lipid precursors and as regulators of metabolism.
Synonyms: HL; HMGCL1
Tractability: Small molecule: a structure with a bound ligand is known; it has a high-quality binding pocket. PROTAC: ubiquitination databases record sites on it; its protein half-life has been measured.
Gene: Protein-coding gene on chromosome 1 (23,801,877 to 23,838,620, reverse strand). Ensembl gene ENSG00000117305.
Subcellular location: Mitochondrion matrix; Peroxisome
Pathways (Reactome):
Metabolism: Synthesis of Ketone Bodies
Protein localization: Peroxisomal protein import
Gene Ontology:
Molecular function: hydroxymethylglutaryl-CoA lyase activity; magnesium ion binding; manganese ion binding; metal ion binding; structural molecule activity; catalytic activity; oxo-acid-lyase activity
Biological process: ketone body biosynthetic process; lipid metabolic process; L-leucine catabolic process
Cellular component: mitochondrion; peroxisome; protein-containing complex; cytosol; mitochondrial matrix; peroxisomal matrix
Genetic constraint (gnomAD): Loss-of-function variants: 22 observed, 30.43 expected, observed/expected ratio (o/e) 0.72, 90% interval 0.52 to 1.03. The upper end of that interval is the gene's LOEUF score, 1.03, which puts it in group 4 of 6, group 1 being the genes least tolerant of losing a copy. Missense variants: 335 observed, 352.25 expected, observed/expected ratio (o/e) 0.95, 90% interval 0.87 to 1.04. Synonymous variants: 131 observed, 130.25 expected, observed/expected ratio (o/e) 1.01, 90% interval 0.87 to 1.16.
Gene-disease validity (ClinGen):
ClinGen rates the evidence that HMGCL causes each of these diseases.
3-hydroxy-3-methylglutaric aciduria (autosomal recessive): Definitive.
Homologues: Orthologues: chimpanzee HMGCL (99% identical), macaque HMGCL (97% identical), guinea pig HMGCL (89% identical), mouse Hmgcl (88% identical), pig HMGCL (86% identical), rat Hmgcl (85% identical), dog HMGCL (82% identical), zebrafish hmgcl (74% identical), tropical clawed frog hmgcl (64% identical), Drosophila melanogaster Hmgcl (59% identical), Caenorhabditis elegans Y71G12B.10 (50% identical). Paralogues in human: HMGCLL1 (67% identical).
Diseases named in the same sentence as HMGCL in open-access papers:
HMGCL is named in the same sentence as 66 diseases in open-access papers, as found by Europe PMC text mining. Sharing a sentence is not in itself a finding about the gene and the disease. The quoted sentences say what the papers report.
HMG-CoA lyase deficiency (8 papers, 2020 to 2025). "3-hydroxy-3-methylglutaryl-CoA lyase (HMGCL) deficiency is both an OA affecting leucine metabolism and a defect of KBs synthesis (acetoacetate and 3-hydroxy-n-butyrate)." (PMID 41425985, 2025). "Background/Objectives: 3-Hydroxy-3-methylglutaryl-CoA lyase deficiency (HMGCLD) is an extremely rare autosomal recessive metabolic disorder caused by mutations in the HMGCL gene." (PMID 41156202, 2025). "The founder mutation (HMGCL c.122G > A (p.Arg41Gln)) was identified in all cases of HMG-CoA lyase deficiency." (PMID 39484073, 2024). "3-Hydroxy-3-Methylglutaryl-CoA Lyase (HMGCL) deficiency can be a very severe disorder that typically presents with acute metabolic decompensation with features of hypoketotic hypoglycemia, hyperammonemia, and metabolic acidosis." (PMID 36771238, 2023). "3-Hydroxy-3-methylglutaryl-CoA (HMG-CoA) Lyase deficiency (HMGLD) (OMIM 246450) is an autosomal recessive genetic disorder caused by homozygous or compound heterozygous variants in the HMGCL gene located on 1p36.11." (PMID 34573903, 2021). "3-hydroxy-3-methylglutaryl-CoA lyase (HMGCL) deficiency or 3-hydroxy-3-methylglutaric aciduria results from mutations in the HMGCL genes, and is an OA affecting leucine metabolism." (PMID 33415129, 2020).
melanoma (7 papers, 2017 to 2024). A malignant, usually aggressive tumor composed of atypical, neoplastic melanocytes. "HMGCL was shown to be increased in androgen-free prostate cancer cells and BRAF-mutated melanoma cells." (PMID 38551020, 2024). "HMGCL expression is upregulated in BRAF V600E melanoma and hairy-cell leukemia." (PMID 35681673, 2022). "Increased levels of HMGCL, an enzyme involved in ketogenesis, were observed in BRAFV600E melanomas with HMGCL knockdown resulting in decreased growth solely in BRAFV600E mutant lines." (PMID 28097822, 2017). "Using an shRNA screen selectively targeting genes involved in metabolism in BRAFV600E and BRAF wild‐type melanoma cell lines, HMG‐CoA lyase (HMGCL) was identified as a possible SL partner to BRAFV600E." (PMID 28097822, 2017). "HMG-CoA lyase (HMGCL), which converts HMG-CoA to acetyl-CoA and a ketone body, could activate MEK1, and promote the proliferation of BRAF-positive melanoma and colon cancer cells." (PMID 36568396, 2022). "In this regard, Kang demonstrated that HMG-CoA lyase (HMGCL), involved in the ketogenesis pathway, activates the interaction between BRAFV600E and MEK leading to the subsequent phosphorylation of MEK1 as shown in hairy-cell leukemia and melanoma cells." (PMID 27738305, 2017).
nasopharyngeal carcinoma (5 papers, 2017 to 2024). A carcinoma arising from the nasopharyngeal epithelium. "It has been demonstrated that the inactivation of HMGCL promotes nasopharyngeal carcinoma proliferation and EMT." (PMID 38551020, 2024). "In contrast, HMGCL expression in nasopharyngeal carcinoma promotes the production of reactive oxygen species (ROS) and inhibiting nasopharyngeal carcinoma cell development and metastasis." (PMID 36508088, 2023). "Here we investigated expression of 3-hydroxy-3-methylglutaryl-coenzyme A (HMG-CoA) 2 lyase (HMGCL), an essential enzyme in ketogenesis, which produces ketone bodies by the breakdown of fatty acids to supply energy, in nasopharyngeal carcinoma (NPC)." (PMID 28931870, 2017). "In contrast to this, our previous study showed that HMGCL gene is silenced in nasopharyngeal carcinoma (NPC) if compared to normal epithelium." (PMID 31921677, 2019). "Similarly, it was shown that other ketogenic enzymes such as ACAT1, HMGCL and/or BDH1/2 levels were significantly downregulated in ccRCC cells and patients, acute myeloid leukemia (AML) patients and AML cell lines, and nasopharyngeal carcinoma (NPC) cells." (PMID 36432618, 2022).
pancreatic cancer (4 papers, 2023 to 2025). "HMGCL has been found to be markedly upregulated in pancreatic cancer, promoting β-OHB production and providing additional energy for proliferation and metastasis of pancreatic cancer." (PMID 41365992, 2025). "HMGCL protein level is high in pancreatic cancer in mice (Pdx1-Cre; lox-stop-lox-KrasG12D/+; Ink4a/Arflox/lox)." (PMID 37958351, 2023). "Further studies to explore the molecular mechanisms regulated by HMGCL are required to validate HMGCL as a druggable candidate to target pancreatic cancer." (PMID 37958351, 2023). "HMGCL is also one of the most significantly upregulated genes in pancreatic cancer, which contributes to produce β-OHB and provides additional energy for proliferation and metastasis of pancreatic cancer." (PMID 36508088, 2023). "HMGCL and β-hydroxybutylate contribute to pancreatic tumor aggressiveness and support metastatic dissemination." (PMID 37958351, 2023). "However, in pancreatic cancer, HMGCL is upregulated and promotes cancer progression through ketogenesis." (PMID 36923932, 2023).
breast carcinoma (3 papers, 2017 to 2024). "HMGCL and other ketone-body-producing enzymes are selectively expressed in the tumor stroma in breast cancer." (PMID 38551020, 2024). "HMGCL has been reported to be overexpressed in stromal cells of breast cancer." (PMID 31921677, 2019).
colon cancer (2 papers, 2017 to 2022). "Besides of NPC, we also analyzed the RNA-sequencing database from the cancer genome atlas (TCGA) and found HMGCL transcription downregulated in several kinds of cancer, including head and neck, kidney and colon cancers (data not shown)." (PMID 28931870, 2017).
glutaric aciduria (2 papers, 2013 to 2022). "Similarly, 10 novel HMGCL variants were reported in 24 patients of different origins suffering from 3-hydroxy-3-methyl-glutaric aciduria." (PMID 35646072, 2022).
heart failure (2 papers, 2009 to 2022). Inability of the heart to pump blood at an adequate rate to meet tissue metabolic requirements. "It preserved the capacity of hepatic ketogenesis and exerted cardioprotective effects against heart failure, increasing cardiac function and decreasing cardiac fibrosis, in liver-specific HMGCL-overexpressed TAC mice." (PMID 35707271, 2022). "HMGCL overexpression preserved the capacity of ketogenesis and exerted cardioprotective effects in continuous KD-fed mice with heart failure." (PMID 35707271, 2022).
pancreatic ductal adenocarcinoma (2 papers, 2022 to 2024). An infiltrating adenocarcinoma that arises from the epithelial cells of the pancreas. "A recent study also showed that HMGCL was upregulated in human pancreatic ductal adenocarcinoma (PDAC) and that depletion of HMGCL impeded migration and invasiveness and reduced tumor cell growth in vivo." (PMID 36432618, 2022). "Moreover, BHB also appears to support pancreatic ductal adenocarcinoma (PDA) growth and metastasis by serving as an alternative energy source, with the enzyme HMG-CoA lyase (HMGCL) playing a key role in ketogenesis." (PMID 39685849, 2024).
benign prostatic hyperplasia (1 paper, 2024). A non-cancerous nodular enlargement of the prostate gland. "In conclusion, miR-1202 is upregulated in benign prostatic hyperplasia; miR-1202 enhances epithelial cell proliferation, suppresses cell apoptosis, and promotes EMT by targeting HMGCL." (PMID 38551020, 2024).
bladder urothelial carcinoma (1 paper, 2023). "While some tumor types, such as bladder urothelial carcinoma and uterine corpus endometrial carcinoma, showed elevated HMGCL expression, other tumor types, such as pheochromocytoma and para-ganglioma as well as cholangial carcinoma, showed decreased HMGCL expression." (PMID 36508088, 2023).
cardiac arrest (1 paper, 2025). Cessation of breathing and/or cardiac function. "A recent meta-analysis of 211 HMGCL deficiency cases revealed that cardiac issues were reported in a few cases, including DCM and cardiac arrest in one patient." (PMID 41425985, 2025).
clear cell renal cell carcinoma (1 paper, 2022). "HMGCL was potential tumor suppressor gene and associated with poor prognosis in clear cell renal cell carcinoma." (PMID 36147494, 2022).
colitis (1 paper, 2024). Inflammation of the colon. "We also observed a decreasing trend in proteins regulating the downstream ketogenesis pathway in colitis, including 3-hydroxy-3-methylglutaryl-CoA lyase (HMGCL), 3-hydroxybutyrate dehydrogenase 1 (BDH1), and carnitine acetyltransferase (CRAT)." (PMID 38668322, 2024).
colon adenocarcinoma (1 paper, 2022). "In colon adenocarcinoma, HMGCL was screened as prognosis-related metabolic gene using risk model analysis." (PMID 36147494, 2022).
colorectal cancer (1 paper, 2022). A primary or metastatic malignant neoplasm that affects the colon or rectum. "Therefore, we used the correlation of the expression level of genes with the prognosis of colorectal cancer patients as an evaluation index, and finally identified eight critical enzymes of amino acid metabolism in colon TAMs, namely, ACADM, ACADS, GPX4, GSR, HADH, HMGCL, HMGCS1 and IDH1." (PMID 36552870, 2022).
glioblastoma multiforme (1 paper, 2025). "Study has also shown that HMGCL enhances H3K27ac modification by promoting acetyl-CoA production, and upregulates FOXM1 expression, which in turn promotes the nuclear translocation of β-catenin, ultimately contributing to glioma stem cell maintenance and glioblastoma multiforme progression." (PMID 41365992, 2025).
HLCS deficiency (1 paper, 2025). "However, the C5OH index is a biomarker for several IMDs, including MCD (BTD and HLCS deficiency), 3-hydroxy-3-methylglutaryl-CoA lyase (HMG-CoA) deficiency, 3-methylcrotonyl-CoA carboxylase (3-MCC) deficiency, and 3-methylglutaconyl-CoA hydratase deficiency." (PMID 41029453, 2025).
kidney cancer (1 paper, 2021). Primary or metastatic malignant neoplasm involving the kidney. "HMGCL led to abnormal metabolism of ketone bodies in kidney cancer, and SUCLG1 led to the coupling of succinyl-CoA hydrolysis with the synthesis of either ATP or GTP during the TCA cycle." (PMID 34094922, 2021).
latent infection (1 paper, 2017). "Hence, inhibition of ketongenesis by downregulating HMGCL may be one of the mechanisms involved in modulating EBV latent infection in NPC cells, thus contributing to tumorigenesis and progression by reducing the immunogenicity of NPC cells." (PMID 28931870, 2017).
lung carcinoma (1 paper, 2023). "NEDD4 promoted the K48-linked ubiquitination of HMGCL in lung cancer cells." (PMID 36923932, 2023). "In summary, this study reveals how TNFα-mediated inflammation reprograms lung cancer metabolism by downregulating the expression of HMGCL." (PMID 36923932, 2023). "In a functional study, overexpression of HMGCL increased the content of β-hydroxybutyrate (β-HB) and inhibited the tumorigenicity of lung cancer cells, and deletion of HMGCL promoted de novo tumorigenesis in KP (KrasG12D;P53f/f) mice." (PMID 36923932, 2023). "Taken together, these results demonstrate that HMGCL inhibits the malignant phenotypes of lung cancer cells." (PMID 36923932, 2023). "In addition, mutation of Ser258 to alanine inhibited the ubiquitination of HMGCL by NEDD4 and thus inhibited the anchorage-independent growth of lung cancer cells more efficiently than did wild-type HMGCL." (PMID 36923932, 2023). "Exogenously expressed HMGCL IKKβ interacted each other in lung cancer cells." (PMID 36923932, 2023). "The observation that the levels of HMGCL protein were increased after lung cancer cells were treated with IKKβ inhibitors prompted us to examine whether IKKβ promotes the degradation of HMGCL protein by directly phosphorylating it." (PMID 36923932, 2023). "More importantly, a complex was formed between endogenous HMGCL and IKKβ in lung cancer cells." (PMID 36923932, 2023). "In the clinical lung cancer samples, the reverse correlation between HMGCL and p-IKKβ was observed." (PMID 36923932, 2023). "In this study, the regulatory effect of inflammatory signals on the metabolism of ketone bodies was investigated to understand how the metabolism of ketone bodies functions in lung cancer progression and how inflammatory signals regulate HMGCL, a key enzyme in the metabolism of ketone bodies." (PMID 36923932, 2023). "In addition, the protein level of HMGCL was lower in most lung cancer cell lines (H157, 95C, 95D and H358) than in HBE (normal human bronchial epithelial cells)." (PMID 36923932, 2023). "The results showed that the protein level of HMGCL was reduced in lung cancer tissues." (PMID 36923932, 2023). "In this study, it was found that the expression of HMGCL was downregulated in lung cancer tissues." (PMID 36923932, 2023). "Moreover, endogenous NEDD4 and HMGCL bound to each other in lung cancer cells." (PMID 36923932, 2023). "Considering the abundance of TNFα in the tumor microenvironment, TNFα-induced phosphorylation and degradation of HMGCL might be a mechanism by which tumor cells crosstalk with the microenvironment, and provide novel insights into the tumor-promoting effects of TNFα in the lung cancer." (PMID 36923932, 2023). "In this study, we found that 3-hydroxy-3-methylglutaryl-CoA lyase (HMGCL), the enzyme that catalyzes the catabolism of leucine and promotes the synthesis of ketone bodies, was downregulated in lung cancer." (PMID 36923932, 2023). "Binding of HMGCL to NEDD4 might weaken the interaction between NEDD4 and these oncogenes, thus stabilizing these oncogenes and promoting the progression of lung cancer." (PMID 36923932, 2023).
lymph node metastasis (1 paper, 2021). "In addition, lymph node metastasis had an increased level of ACAT1 expression (P = 0.0429), while HMGCL was higher in liver metastasis compared with primary tumors (P = 0.0274)." (PMID 34584218, 2021).
renal cell carcinoma (1 paper, 2021). "Our previous and present findings show that overexpressing the ketogenesis genes HMGCL and ACAT1, resulted in increased intracellular β-HB in both renal cell carcinoma and NPC, thereby inhibiting the growth capacity of tumor cells." (PMID 34485115, 2021).